IL10 (interleukin 10)
Diseases named in the same sentence as IL10 in open-access papers (continued):
Sharing a sentence is not in itself a finding about the gene and the disease.
infection (continued). "Several studies pointed that M.tb successfully engages activators of IL-10 transcription such as STAT3 and ReIB during infection to abolish the protective response mounted by the host and ensures its survival and persistence." (PMID 31921181, 2019). "Before infection, 7% (IQR, 3%–12%) of CD16+ DCs spontaneously produced IL-10, IL-12, or TNF ex vivo, with TNF (5% [IQR, 4%–10%]) dominating the response." (PMID 30239833, 2019). "Among the cytokines analyzed for this study, IL-4, IL-5, IL-10, IL-13, and TGF-b participate in the resolution of infection-related pulmonary inflammation." (PMID 31271354, 2019). "Other markers that were upregulated during the early active infection phase included IFN-γ, IL1-RA, IL-6, IL-10, IL-15, and IL-18; all of which have been reported in cases of human disease." (PMID 31557262, 2019). "It is noteworthy that at early infection there was an enhanced induction of pro-inflammatory cytokine response of TNF-α and IFN-γ, which gradually reduced to basal levels with the surge of regulatory cytokines, IL-4, IL-10, and TGF-β in later infection." (PMID 31031744, 2019). "Along with higher virus loads, increased IL-10 levels have consistently emerged as a prognostic factor for poor clinical outcomes in EBOV, SUDV and/or BDBV infection." (PMID 31547585, 2019). "The level of IL-10 expression was similar in that in MAH/LPS-infection and LPS-treatment of TLR2−/− DCs and in MAH/LPS-infection and MAH-infection of TLR4−/− DCs, whereas IL-10 production was strongly increased in MAH/LPS-infection in WT DCs." (PMID 31440223, 2019). "The NH36 vaccine also enhanced the TNF-α secretion whereas, after infection, the F3 vaccine induced the strongest IFN-γ and TNF-α secretions while the chimera was dominant for production of IL-10." (PMID 31024556, 2019). "After 14 days of infection (9 days of PMN depletion), the levels of IFN-γ decreased, but the regulatory interleukin 10 (IL-10) and other cytokines, such as IL-12 and IL-6, significantly increased." (PMID 30804100, 2019). "In subcluster 13, compared with the smooth line in IL10–1, CC3 showed a down-regulated pattern suggesting more genes were suppressed in response to RKNs infection." (PMID 30075750, 2018). "Furthermore, IL-10 production in our infection model was disrupted by deletions of both the B- and C-repeat regions, suggesting the involvement of distinct functional surfaces in the M5 protein for driving IL-10 production in macrophages and T cells, respectively." (PMID 29579113, 2018). "An optimal production of IL-10 in lungs of IAV-infected mice treated with MDP was also found to coincide with the kinetic of Treg cell mobilization and the resolution of phase of infection." (PMID 29445379, 2018). "Upon infection, however, we detected GATA-3+Treg as the dominant IL-10+ Treg source in the small intestine and mLN of SPF as well as GF mice." (PMID 30349532, 2018). "Taken together, the results indicate that downregulation of mmu-miR-21a-5p induced by infection increases GBP5 levels and decreases IL-10 expression thus contributing to bacterial control in host cells." (PMID 29942317, 2018). "Infection of epithelial cells by strains ATCC 17978 and PAO1 showed that IL-6, tumor necrosis factor alpha (TNF-α), and IL-10 levels were similar for hypoxia and normoxia at 2 and 24 h postinfection." (PMID 30082478, 2018). "Infection with EHV-1 Ab4 induced an intranasal cytokine response characterized by a sharp increase in IFN-α on d2pi (p<0.0001) and elevated IL-10 staring on d2pi (p<0.01) on d2pi compared to the Ab4ΔORF1/71 infected and non-infected control groups." (PMID 30440016, 2018). "At three weeks post-infection with L. major, the number of IFN-γ-producing, and to a lesser extent IL-10-producing, TCRß+CD4+ splenic T cells was higher in mice coinfected with T. b." (PMID 30619253, 2018).
infection (continued). "Spearman rank correlations between age, gender, IFN-γ, TNF-α, IL-10, IL-17A, ratio IFN-γ/IL-10, and exposure time in the infection place less or equal -and longer- than 90 days." (PMID 30186774, 2018). "To evaluate the role of NF-κB on IL-8 and IL-10 expressions, we incubated BEC with 20 μM Parthenolide, an NF-κB inhibitor, for 1 h before infection." (PMID 29434603, 2018). "In contrast, mb1creIL-4Rα−/lox mice developed significantly increased levels of IL-4, IL-10, IL-6, IL-17, and IFN- γ compared to IL-4Rα−/lox littermate control mice at 24 weeks post infection." (PMID 30619289, 2018). "In mesenteric lymph nodes (MLN), IL-10 and TNF-α levels were elevated while splenic cytokine expression was unaltered upon infection." (PMID 29973271, 2018). "Previous single nucleotide polymorphism (SNP) studies have shown that over- or underexpression of immunoinflammatory genes such as TNF-α, interleukin- (IL-) 1, IL-10, IL-8, interferon gamma, and CD14 receptor is related to infection development in hospitals." (PMID 29950924, 2018). "Infection of macrophages favors the secretion of anti-inflammatory cytokines such as IL-10 and TGF-β, which impair the development of protective immune responses and help the spread of the infection." (PMID 29599775, 2018). "During infection by L. (L. ) donovani, on the other hand, p38 MAPK activation is mediated by TLR2, lowering IL-12 production while increasing IL-10 production." (PMID 29543867, 2018). "Recently, it has been suggested that, during the chronic stages of infection, IFNs, via STAT1, can have a predominantly suppressive role, inducing pathways involving IL-10 and programmed cell death ligand 1 (PDL1)." (PMID 30235866, 2018). "In the liver on day 7 post-infection, the expression of iNOS, IL-1β, IL-6, IL-12 p40, TNF-α, IL-10, TGF-β, CCR2, CCL2, IFN-γ and IL-4 was significantly up-regulated, and the expression of Arg-1 was down-regulated in both of MRP14-KO mice and WT mice." (PMID 29902248, 2018). "In contrast, the initial HAM response to infection displays a lag phase with few genes significantly up-regulated at the 2 h post-infection time point (CSF2, IL-1B, IL-6, IL-10, IL-21)." (PMID 29847580, 2018). "L. major amastigotes were shown to modulate the CD40-CD40L pathway downstream by inducing ERK1/2 and IL-10 production, which inhibits the p38MAPK/IL12 pathway resulting in persistence of infection." (PMID 30619775, 2018). "Supernatants from PPD-B stimulated samples were also checked for IL-1β, IL-6, IL-10, IL-12, and TNF-α production over the course of infection using the MSD multiplex platform." (PMID 29343690, 2018). "By contrast, at 6 h post infection, the DN-CREB-Ser133Ala-expressing cells showed a significant reduction of IL-10 expression." (PMID 29434603, 2018). "More recently, the parasite burden and levels of IFN-γ, TNF-α, IL-10, and TGF-β were evaluated in 5 target tissues at 6 and 16 months after infection with L. infantum in an experimental canine model." (PMID 30175073, 2018). "Concentrations of inflammatory and immunomodulatory cytokines IL-1β, IL-6, TNF-α, IL-10, and IL-13 were significantly greater in BAL samples of Nrf2 KO mice compared to WT controls at day 1 after infection (p < 0.05)." (PMID 29740449, 2018). "However, given that the infection route was intraperitoneally and not intranasal, we cannot conclude whether the production of IL-10 is beneficial or detrimental during pneumonia caused by MDR P. aeruginosa in this particular experiment." (PMID 30279680, 2018). "Plasma levels of TNF-α, IFN-γ, IL-6, IL-10, CXCL10, CCL2 and IL-4 were all increased upon infection." (PMID 30375380, 2018). "Ab4ΔORF1/71 infection had reduced nasal shedding (1/5 vs. 5/5) and, simultaneously, decreased intranasal interferon (IFN)-α, interleukin (IL)-10 and soluble CD14 secretion." (PMID 30440016, 2018). "We found in spleens from BALB/c mice 2 days after infection significant amounts of IFN-γ, IL-1α, IL-1β, IL-10, IP-10, and MIG." (PMID 30500862, 2018).
infection (continued). "In these infections, the Th1 response (mediated by TNF-α, IL-2, IL-12, and IFN-γ) exerts a protective role, while the Th2 response (mediated by IL-4, IL-5, and IL-10) is known as a disease promoter." (PMID 30186271, 2018). "Treatment of patients, undergoing BMT with Interleukin-10 (IL-10)-anergized donor T cells, led to immune reconstitution without the development of GVHD, which resulted in protection against infection and against the return of the cancer." (PMID 30386800, 2018). "The effects of diminished CD200–CD200R signaling by LdCen−/− were most evident in the suppression of IL-10-producing CD4+ T cells that helped enhance more Th1 cytokine producing and multi-functional T cells compared to wild-type infection." (PMID 29915577, 2018). "Increase of 5–10-fold levels in TNFα production in response to human Babesia WA1 strain later in infection, suggested to be produced by CD8+ T cells, and concomitant decrease in IL-10 levels was occurred together with fatal disease in mice." (PMID 29445365, 2018). "In early stage infection, TLR3-/- mice showed a diminished synthesis of IFN-β, IL-1β, and IL-6, but enhanced production of IL-10, TNF-α, and IFN-γ." (PMID 29624589, 2018). "Thus, the induction of IL-10 expression in macrophages stimulated with EVs from L. amazonensis promastigotes could contribute to the suppression of the initial response, allowing parasite survival at the site of infection." (PMID 30627118, 2018). "In this work, we have presented experimental evidence indicating that BEC infected with S. aureus activates NF-κB and expresses IL-8 at initial stages of infection (2 h) and activates CREB and IL-10 expression at later stages (6 h)." (PMID 29434603, 2018). "Patient ZIKV17 showed concentrations of IP-10, MIG, IL-6, IL-10, INF-γ, IL-8, MCP-1and RANTES higher than control, with the highest values found at the beginning of the infection (p < 0.05), highlighting a local persistent inflammation in the MRS." (PMID 30405055, 2018). "In contrast, production of IL-10, a counter-regulator of IFN-γ during the early onset of infection, is beneficial for the pathogen, promoting intracellular replication by setting a level conducive for the survival of the pathogen." (PMID 29801438, 2018). "At day 6 post-infection, C57BL/6J mice also exhibited higher levels of IL1A, IL1B, CCL2, CCL3, IL2, IL10, and IL6." (PMID 30713529, 2018). "To gain a better measure of immunoregulatory balance, we analyzed the TNF-alpha/IL-10 ratio and found that both L. infantum strains induced a lower TNF-alpha/IL-10 ratio in monocytes when compared with infection with L. braziliensis." (PMID 29358935, 2017). "To further confirm that IRAK-M, PPARγ and IL-10 were induced via the interaction of S glycoprotein with DPP4, we used siRNA approach to knock-down DPP4 in THP1 macrophages prior to infection." (PMID 28118607, 2017). "Through the immunosuppressive properties of IL-10, MMTV is then able to establish a persistent infection and immunological tolerance." (PMID 29211815, 2017). "The levels of IL-10 and TGF-β increased as infection progressed while proliferation capacity continued to diminish in the face of an expanding lymphocyte number." (PMID 28871261, 2017). "Analysis of cytokines production by spleen and MLN cells in mice model have shown the production of IL-4, IL-10, IL-13, IL-17, IL-22, TNF-α, and IFN-γ after infection with both WB and GS strains." (PMID 28979269, 2017). "IL-10 e TGF-β are regulatory cytokines that possesses the ability to decrease inflammatory cytokines and appears to be deleterious in the early infection." (PMID 29255475, 2017). "According to data from the literature we considered levels of cytokines IL1β and IL10 and chemokine IL8 to be of greatest interest in STEC-infection." (PMID 28559930, 2017). "We evaluated the effect of treatment with BNZ in IL-10, TGF-β and Foxp3 gene expression during the acute phase of infection." (PMID 29255475, 2017).
infection (continued). "IL-10 production has also been shown to be important for murine cytomegalovirus (MCMV) infections; by reducing anti-viral responses, establishment of infection is permitted and immune pathology is inhibited." (PMID 28628650, 2017). "At onset of infection, serum levels of both pro- (TNFα, IL6, IL8) and anti-inflammatory (IL10) cytokines were significantly lower in SIRS-N compared to SIRS-P patients." (PMID 31058274, 2017). "Infection with the JLP or Y strains increased expression of IFN-γ in the heart and of IL-10 and IL-17 in the spleen and heart compared to uninfected animals." (PMID 29255475, 2017). "In our study, the expression levels of IL-1β, IL-10, and IFN-β in the lungs and MHC-II in the brain were upregulated to a remarkably high level after infection with ZH283 and SW8, although were greater for ZH283 than SW8." (PMID 28676793, 2017). "To achieve this, we evaluated the gene expression of pro-inflammatory (IL-1β and IL-6) and one anti-inflammatory cytokine (IL-10), as well as 2 chemokines (IL-8 and RANTES), in NaO-treated bMECs during infection." (PMID 28361042, 2017). "After challenge with B. microti, the levels of cytokines including IL-17, IL-4, IL-6, IL-10, IL-12p70, G-CSF, IFN-γ, TNF-α, IL-2, GM-CSF, MCP-1, MIP-1α, MIP-1β, and MIP-2 in the serum of the BMSA vaccinated group changed as infection progressed." (PMID 29312230, 2017). "Production of Th2 cytokines (IL-4, IL-5, IL-10 and IL-13) by MLN cells similarly peaked at day 6–7 post infection and gradually declined thereafter." (PMID 28651009, 2017). "As an important anti-inflammatory cytokine, IL-10 inhibits the activity of Th1, Th2 and CD8+ T cells during the infection procedures." (PMID 29340060, 2017). "Infection of macrophages with Ms_rv0774c resulted in significantly increased expression of TLR2 receptor and IL-10 cytokines." (PMID 28713776, 2017). "Even so, carvedilol therapy during acute phase of infection was able to modulate the CCL2 and intensify the production of the regulatory cytokine IL-10 in serum from infected mice." (PMID 28377930, 2017). "However, in our study, what is worth noting is the suppressible inflammatory cytokine IL-10 also has a significant up-regulated in the tested tissues, and this might explain the phenomenon that the infection of remaining ducks were gradually alleviated at the later stages of the infection." (PMID 28878764, 2017). "To ascertain this FACS data, we determined the relative expression of Th2 and Treg related cytokines (IL-4, IL-5, IL-10 and TGF-β) in the liver of non-infection and C. sinensis infection mice by the quantitative RT-PCR." (PMID 28151995, 2017). "We also found that upregulation of miR-27a reduced MAP-induced IL-10 expression at both 6 and 18 h postinfection and simultaneously reduced L-10 protein levels in BMDM cells after infection with MAP." (PMID 29375563, 2017). "Infection with HV-PRRSV induced a significantly higher levels of TNF-α and IL-10 in both sera and lung tissues and higher IFN-α and IFN-γ in the serum." (PMID 28839507, 2017). "Thirty days post infection, chitosan treatment resulted in MPO, MCP-1, TNF-α, IL-12p70 and IL-4 levels falling to control values, but IL-6, IL-10 and TGF-β were elevated." (PMID 29156562, 2017). "To verify that the observed effects are specific and exclude a general influence of protein solutions on B cell IL-10 production and activation, we treated mice with human serum albumin (HSA) as infection-unrelated control protein." (PMID 28753651, 2017). "The infection stimulated the release of TNF-α, IL-1β, IL-6, IL-8, and IL-10 production by infected cells." (PMID 29118740, 2017). "In the sera of M. fortis, the levels of IL-1b, IL-3, IL-4, IL-10, IL-17, MCP-1 and VGF were found to increase from the second to the third week post-infection." (PMID 28900150, 2017). "In the present study, both contents and mRNA expression levels of IL-2, IL-8, IL-10, and IFN-γ were influenced by SNE infection and controlled by BS15." (PMID 29209325, 2017).
infection (continued). "CSF concentrations of IL-10, IL-6, and IFN-γ were significantly increased in patients with late-stage infection, compared with those with early stage infection." (PMID 28927234, 2017). "Serum levels of IFN-γ, IL-4, IL-10 and IL-17 were determined by IVCCA at 0, 3, 5, 7, 10 and 12 wks post infection." (PMID 28614408, 2017). "In addition, previous studies have demonstrated that MSCs may participate in the mitigation of infection by secretion of soluble paracrine factors including interleukin (IL)-10, prostaglandin E2 (PGE2), tumor necrosis factor (TNF)-α-stimulated gene/protein 6, and IL-6." (PMID 28114965, 2017). "IL10 production by IFNγ+ CD4 T cells was higher in younger children and in those with high-parasite burden during recent infection." (PMID 29097996, 2017). "IL-10 plays an important role in the regulation of P. yoelii infection, and CD4+ T cells have been shown to secrete high amounts of IL-10 upon infection." (PMID 28293237, 2017). "At all periods after infection analyzed, a decreased number of CD11b+ cells expressing intracellular IL-12, TNF-α, IL-1β, TGF-β, and IL-10 was detected in the lungs of IDO1−/− mice when compared to the WT counterparts." (PMID 28791025, 2017). "The present study evaluated the effect of treatment with benznidazole on mRNA expression of IFN-γ, IL-17, IL-10, TGF-β and FoxP3 in spleen and heart tissue of BALB/c mice in the acute phase of an experimental infection with Trypanosoma cruzi, strains JLP or Y." (PMID 29255475, 2017). "In the bovine model of infection, we have previously shown at a peripheral level, that both TGF-β and IL-10 played a role in limiting IL-4 and IFN-γ production." (PMID 28871261, 2017). "In the comparison of the levels of the cytokines, IL-6, IL-10, and CRP were statistically higher in patients with infection than the post-treatment values." (PMID 28148470, 2017). "At 24 h after infection, the expression of cytokines and chemokines (i.e., TNF-α, IL-1β, IL-6, and IL-10) was evaluated by using ELISA." (PMID 28615695, 2017). "The frequencyof IL-10 and IFN-γ double producers within CD4+ Tcells also increased 7 days upon infection in all tissues analysed, except OAT,and was still detected increased in GAT and MAT by 21 days (Figs5e and 6e)." (PMID 27001522, 2016). "This revealed 13 mediators of inflammation that correlated with infection status, which were, in order of strength of significance, IL-4, IL-5, IL-7, IL-15, IFN-α, IL-12, IFN-γ, IL-17, IL-1Ra, TNF-α, IL-1β, IL-10, and IL-2." (PMID 27418744, 2016). "In this study, total spleen cells were shown to secrete TNF-α, IFN-γ, IL-6, IL-10, CCL3, and CXCL9, suggesting an activation of splenic cells during the infection and a polarization towards a Th1 response." (PMID 27905502, 2016). "The relative IL-10 and TNF-α mRNA expression levels produced by the DCs were significantly up-regulated 24 h post-infection with the H9N2 virus." (PMID 27826541, 2016). "Splenic IL-10+ CD4+ T cell frequencies also contracted rapidly, remaining at low but significant levels during the remaining course of infection." (PMID 27926930, 2016). "The ability of effector CD4+ T cells to co-express IL-10 and IFN-μ is well established, and such cells have been described in several infection models." (PMID 26866695, 2016). "Of note, upregulation of Th2 cytokines IL10 and IL13 by infection was more profound in CHB than in CS." (PMID 27197554, 2016). "In agreement with the reporter data, Ag-experienced splenic CD4+ T cells obtained on day 7 of infection produced high levels of IFN-γ and IL-10 protein." (PMID 27630165, 2016). "H5N1 induced significantly higher levels of TNF-α, IL-6, IL-8, IL-10 and MCP-1 than those of H7N9 viruses at 48 h post-infection." (PMID 26975414, 2016). "In accordance with data derived from polyclonally-stimulated CD4+ T cells, high frequencies of virus-specific IL-10+CD4+ T cells were observed in salivary glands after MCMV infection, peaking at d14 post-infection (pi)." (PMID 27926930, 2016).